NUDT5 (nudix hydrolase 5)
Description:
Enzyme that can either act as an ADP-sugar pyrophosphatase in absence of diphosphate or catalyze the synthesis of ATP in presence of diphosphate. In absence of diphosphate, hydrolyzes with similar activities various modified nucleoside diphosphates such as ADP-ribose, ADP-mannose, ADP-glucose, 8-oxo-GDP and 8-oxo-dGDP. Can also hydrolyze other nucleotide sugars with low activity. In presence of diphosphate, mediates the synthesis of ATP in the nucleus by catalyzing the conversion of ADP-ribose to ATP and ribose 5-phosphate. Nuclear ATP synthesis takes place when dephosphorylated at Thr-45. Nuclear ATP generation is required for extensive chromatin remodeling events that are energy-consuming. In vitro, it has decapping activity on 11-mer RNA capped with uridine diphosphate N-acetylglucosamine (UDP-GlcNAc) by hydrolyzing the pyrophosphate bridge of the sugar cap. Does not play a role in U8 snoRNA decapping (By similarity). Binds U8 snoRNA (By similarity).
Synonyms: hNUDT5; hYSAH1; YSA1H; YSA1; YSAH1
Tractability: Small molecule: a structure with a bound ligand is known; it has a high-quality binding pocket. PROTAC: UniProt records ubiquitination sites on it; ubiquitination databases record sites on it; its protein half-life has been measured.
Target class: Enzyme; Transferase
Chemical probes: MRK-952 (high quality), TH5427 (high quality)
Gene: Protein-coding gene on chromosome 10 (12,165,328 to 12,196,127, reverse strand). Ensembl gene ENSG00000165609.
Subcellular location: Nucleus
Subcellular location (Human Protein Atlas): Nucleoplasm; Vesicles; Centrosome; Mid piece
Pathways (Reactome):
Metabolism: Phosphate bond hydrolysis by NUDT proteins
Gene Ontology:
Molecular function: 8-oxo-dGDP phosphatase activity; ADP-ribose diphosphatase activity; ADP-sugar diphosphatase activity; identical protein binding; magnesium ion binding; nucleotidyltransferase activity; protein binding; protein homodimerization activity; 5'-(N(7)-methylguanosine 5'-triphospho)-[mRNA] hydrolase activity; snoRNA binding; hydrolase activity; nucleoside diphosphate phosphatase activity
Biological process: ATP generation from poly-ADP-D-ribose; chromatin remodeling; D-ribose catabolic process; ribonucleoside diphosphate catabolic process; nucleobase-containing small molecule metabolic process; nucleotide metabolic process; ribose phosphate metabolic process
Cellular component: extracellular exosome; nucleus; cytosol
Genetic constraint (gnomAD): Loss-of-function variants: 10 observed, 17.37 expected, observed/expected ratio (o/e) 0.58, 90% interval 0.35 to 0.98. The upper end of that interval is the gene's LOEUF score, 0.98, which puts it in group 4 of 6, group 1 being the genes least tolerant of losing a copy. Missense variants: 168 observed, 197.21 expected, observed/expected ratio (o/e) 0.85, 90% interval 0.75 to 0.97. Synonymous variants: 62 observed, 75.37 expected, observed/expected ratio (o/e) 0.82, 90% interval 0.67 to 1.02.
Homologues: Orthologues: chimpanzee NUDT5 (99% identical), macaque NUDT5 (97% identical), dog NUDT5 (91% identical), guinea pig NUDT5 (89% identical), rat Nudt5 (86% identical), mouse Nudt5 (82% identical), pig NUDT5 (74% identical), tropical clawed frog nudt5 (66% identical), zebrafish nudt5 (56% identical), Caenorhabditis elegans ndx-2 (34% identical). Paralogues in human: NUDT14 (21% identical).
Diseases named in the same sentence as NUDT5 in open-access papers:
NUDT5 is named in the same sentence as 27 diseases in open-access papers, as found by Europe PMC text mining. Sharing a sentence is not in itself a finding about the gene and the disease. The quoted sentences say what the papers report.
breast carcinoma (32 papers, 2018 to 2025). "Free energy landscape analysis further supported their potential as NUDT5 inhibitors, offering avenues for novel therapeutic strategies against NUDT5-associated breast cancer." (PMID 39225905, 2025). "Among these six identified phosphatases, NUDT5 consistently exhibited an association with breast cancer outcomes, with high NUDT5 expression correlating with poor outcomes." (PMID 38317231, 2024). "NUDT5 has also been found to be overexpressed in breast cancer patients, and this is associated with a worse prognosis as well as a higher risk of recurrence and metastasis." (PMID 36615284, 2022). "The expression of NUDT5 has been linked to chromosomal remodeling, cell adhesion, the maintenance of cancer stem cells, and the epithelial-to-mesenchymal transition in breast cancer cells, according to earlier research." (PMID 36177227, 2022). "This study explored the association of NUDT5 with the tumor development and poor prognosis in patients with breast cancer." (PMID 33571243, 2021). "NUDT5 overexpression is associated with a more aggressive breast cancers, and we have provided further insight into the possible explanation for this correlation using 3D cell culture of breast cancer cells." (PMID 33668737, 2021). "We investigated the association between NUDT5 expression and the pathologic characteristics of 140 breast cancer samples by performing IHC." (PMID 33571243, 2021). "We evaluated the association between the expression of NUDT5 and the clinicopathological features and survival of breast cancer patients." (PMID 33571243, 2021). "It is also knownthat NUDT5 (also referred as NUDIX5) has been linked to hormone dependent gene regulation andproliferation in breast cancer cells." (PMID 31902977, 2019). "In this investigation, 2895 natural compounds obtained from marine bacteria were selected from the CMNPD database and subjected to virtual screening against the NUDT5 enzyme, which has been shown to be implicated in cancer aggressiveness, particularly in breast cancer." (PMID 39225905, 2025). "Additionally, NUDT5 was shown to be associated with the prognosis of breast cancer, lung cancer and prostate cancer." (PMID 38317231, 2024). "NUDT5 affects the phase separation process by regulating ATP synthesis in the nucleus of breast cancer cells." (PMID 40211955, 2025). "We confirmed depleted pyrimidines alongside elevated purines in three additional cell lines depleted of NUDT5, including the breast cancer line MCF7, in which earlier work on NUDT5 was performed." (PMID 41233602, 2025). "Nucleotide diphosphate hydrolase type 5 (NUDT5) plays a significant role in the estrogen-signaling pathway and is overexpressed in breast cancer." (PMID 41009411, 2025). "This study aimed to explore the anti-breast cancer potential of quercetin and its 52 structural analogs by targeting the NUDT5 enzyme using the in silico molecular docking method." (PMID 41009411, 2025). "To delve further into the expression patterns, we stratified NUDT5 RNA expression levels in the METABRIC dataset across the PAM50 breast cancer subtypes (normal-like, luminal A, luminal B, HER2-enriched, claudin-low, and basal-like)." (PMID 38317231, 2024). "The discovery of NUDT5's significant role in breast cancer biology prompted the exploration of small molecule inhibitors targeting NUDT5." (PMID 38317231, 2024). "The mRNA expression levels of NUDT5 in breast cancers were investigated using TCGA and METABRIC (Curtis) datasets." (PMID 38317231, 2024). "Through bioinformatic analysis, molecular simulation, and cell-level experiments, seven approved drugs were identified as potential NUDT5 inhibitors and were proved to have a cytotoxic effect on estrogen-receptor-positive breast cancer cell line MCF7." (PMID 35629965, 2022). "The design of novel coumarin derivatives against breast cancer restricts ATP synthesis via the targeted NUDT5 antagonist." (PMID 36615284, 2022).
breast carcinoma (continued). "Our current work added to the scientific knowledge of the research community, as coumarin derivatives targeted the NUDT5 pathway of breast cancer cells." (PMID 36615284, 2022). "Together, all these results exhibited the potential of NUDT5 as a drug target and a prognostic biomarker in precision medicine of breast cancer." (PMID 35629965, 2022). "Our group found that estrogen-receptor-positive breast cancer patients with low-level NUDT5 expression had significantly longer survival times compared with high-NUDT5-level counterparts." (PMID 35629965, 2022). "Elevated NUDT5 level has been reported as a poor prognostic marker of breast cancer, non-small cell lung cancer, esophageal squamous cell carcinoma, and clear cell renal cell carcinoma." (PMID 36036011, 2022). "Recently, NUDT5 was discovered to function as a rheostat for hormone-dependent gene regulation and proliferation in breast cancer cells." (PMID 36177227, 2022). "In the present study, we investigate the expression of NUDT5 in breast cancer cell lines and specimens." (PMID 33571243, 2021). "One such target is the enzyme NUDT5 (also known as NUDIX5, Nudix-linked to moiety X-5), which we have shown to be essential for HR+ breast cancer growth and breast cancer stem cell (BCSC) initiation and maintenance." (PMID 33668737, 2021). "In recent years, the role of NUDT5 in the biology of breast cancer cells has attracted our attention in the context of our studies on the function of the poly-ADP-Ribose (PAR) synthesis by PARP1 for the hormonal gene regulation." (PMID 33668737, 2021). "In order to gain more insight into the mechanism of PARP1 and NUDT5 activation in breast cancer cells, a more comprehensive analysis of the phosphorylation events and signaling cascades is required." (PMID 33668737, 2021). "The results showed that NUDT5 was higher expressed in breast cancer tissues than in adjacent tissues." (PMID 33571243, 2021). "Inhibition behavior of all new synthesizes was studied by MOE module as in-silico approach which conducted versus the crystal structure of NUDT5 protein (6gru) of breast cancer cells." (PMID 34901511, 2021). "These signatures, along with angiogenesis, is characteristic of aggressive breast cancer types and depends on nuclear ATP synthesis by NUDT5." (PMID 33668737, 2021). "NUDT5 generates ATP in the nucleus of breast cancer cells in response to progesterone, dependent on degradation of PARP1 synthesize PAR to ADPR by PARG." (PMID 33668737, 2021). "Phosphorylation of AKT at Thr308 and the expression of Cyclin D1 levels were reduced by low NUDT5 expression in 3 breast cancer cell lines." (PMID 33571243, 2021). "Taken together, this data shows a multifaceted role of NUDT5 in aggressive breast cancer progression." (PMID 33668737, 2021). "Breast cancer patients with high NUDT5 expression had a worse prognosis than those with low expression of NUDT5." (PMID 33571243, 2021). "IHC of 30 paired breast cancer tissues at different pathological stages found that 100% of the para-cancer tissues (N = 30) had low NUDT5 expression, while 22 tumor tissues (73.33%) had high-expression of the NUDT5 (Student’s t-test; P < 0.001)." (PMID 33571243, 2021). "Previous studies have shown NUDT5 expression affected chromosome remodeling, involved in cell adhesion, cancer stem cell maintenance and epithelial to mesenchyme transition in breast cancer cells." (PMID 33571243, 2021). "NUDT5 also involved in cell adhesion, cancer stem cell maintenance and epithelial to mesenchyme transition in breast cancer cells." (PMID 33571243, 2021). "NUDT5 is essential not only the response to progesterone but of breast cancer cells to hormones, but also generation and maintenance in BCSC from multiple breast cancer cell lines grown in 3D culture." (PMID 33668737, 2021). "High NUDT5 expression was observed in 22 of 30 breast cancer specimens compared to all the para-cancer tissues specimens." (PMID 33571243, 2021).
breast carcinoma (continued). "Three typical cell lines were used to assess the role of NUDT5 in the proliferation, migration, and invasion of breast cancer cells." (PMID 33571243, 2021). "The therapeutic potential of NUDT-selective inhibitors has already been shown—NUDT1-selective inhibitors have shown efficacy in multiple studies in vitro and in vivo, and the NUDT5-selective inhibitor TH1457 blocks cell proliferation in breast cancer cells." (PMID 33668737, 2021). "Kaplan-Meier analysis with a log-rank test was performed to assess the relationship between NUDT5 expression and the overall survival (OS) of breast cancer patients." (PMID 33571243, 2021). "Proliferation, migration, invasion, AKT phosphorylation at Thr308 and Cyclin D1 expression of breast cancer cell lines are enhanced by NUDT5 expression." (PMID 33571243, 2021). "Our results consistent with the previous study that found the expression of NUDT5 protein was lower in normal tissues than in tumor tissues, including breast cancer." (PMID 33571243, 2021). "however, multivariate analysis indicated that high NUDT5 expression was an independent prognostic factor for the OS of patients with breast cancer (hazard ratio [HR] 0.114; 95% confidence interval [CI] 0.021–0.612; P = 0.0113)." (PMID 33571243, 2021). "In breast cancer, NUDT5 overexpression not only increases ATP synthesis and reconstructs tumor cell chromosomes, it also activates the AKT pathways and increases the expression of Cyclin D1, which promotes cancer cell resistance to ER-targeting drugs." (PMID 33571243, 2021). "Knocked down NUDT5 expression dramatically inhibited the proliferation, migration, and invasion of breast cancer cell lines in vitro." (PMID 33571243, 2021). "Recent studies have revealed the important role of NUDT5 in estrogen signaling and breast cancer, but research on the corresponding targeted therapy has just started." (PMID 32300600, 2020). "Exploring the interactome of PAR in breast cancer cells we identified NUDIX5 (also known as NUDT5) as a hormone-induced interactor." (PMID 32485671, 2020). "NUDT5 is overexpressed in breast cancer compared to normal tissue and stratifying patients on the basis that elevated expression levels of NUDT5 predicts a poorer prognosis for patients." (PMID 31510016, 2019). "In order to understand the role of NUDT5 in cancer cell growth, we performed phenotypic and global expression analysis in breast cancer cells grown as oncospheres." (PMID 31510016, 2019). "To further demonstrate the utility of NUDT5-targeted probes, we analyzed our top compounds within the context of hormone signaling and breast cancer with T47D breast adenocarcinoma cells." (PMID 29343827, 2018). "Here, we further elucidate the physiological relevance of known NUDT5 substrates and underscore the biological requirement for NUDT5 in gene regulation and proliferation of breast cancer cells." (PMID 29343827, 2018). "Here, the authors identify potent, small molecule inhibitors of NUDT5, which is implicated in ADP-ribose and 8-oxo-guanine metabolism, and confirm its role in gene regulation and proliferation in breast cancer cells." (PMID 29343827, 2018). "Investigating the role of NUDT5 in breast cancer has highlighted its importance in ADPR metabolism and hormone-dependent gene regulation." (PMID 29343827, 2018). "Notably, we further investigated the inhibitory potential of its triterpenoids using in silico models targeting four key proteins associated with breast cancer (HPA, MELK, CK2α, and NUDT5)." (PMID 41237100, 2025). "Therefore, NUDT5 has been identified as a key factor in ATP production in the nucleus of breast cancer cells." (PMID 41237100, 2025). "To investigate the impact of NUDT5 on the growth of breast cancer cells, we employed siRNA-mediated knockdown in a panel of breast cell lines, including 3 ER-positive cell lines (MCF-7, ZR-75-1 and MDA-MB-361) and 3 TNBC cell lines (MDA-MB-231, MDA-MB-436 and MDA-MB-468)." (PMID 38317231, 2024).
breast carcinoma (continued). "The reported targets with these scaffolds revealed potent cytotoxic activities against various human cancer cell lines with different mechanisms, such as the inhibition of the dihydrofolate reductase enzyme and NUDT5 (Nudix Hydrolase 5) to silence hormone signaling in breast cancer." (PMID 36296551, 2022). "Recent research has revealed another function of NUDT5: it drives nuclear ATP synthesis, which may play a role in breast cancer." (PMID 36615284, 2022). "Here, we designed and conducted computational studies of several complexes of iron metal (III) and thiourea-derived compounds with NUDT5 to assess the possibility of developing thiourea compounds as therapeutic drug candidates for breast cancer through NUDT5 inhibition." (PMID 36177227, 2022). "In addition, the knockdown of NUDT5 suppressed breast cancer cell lines proliferation, migration and invasion, and dramatically inhibited the AKT phosphorylation at Thr308 and expression of Cyclin D1." (PMID 33571243, 2021). "High NUDT5 expression was observed in 56 of 140 breast cancer specimens." (PMID 33571243, 2021). "Moreover, we observed that NUDT5 was identified in the PAR interactome of breast cancer cells exposed to hormone, leading us to investigate the role of NUDT5 in hormone action." (PMID 33668737, 2021). "On the basis of these findings, we speculated that Cyclin D1 expression was upregulated in NUDT5-highexpressing breast cancer tissues." (PMID 33571243, 2021). "We explored the molecular mechanisms by which NUDT5 influence breast cancer." (PMID 33571243, 2021). "Our results show that the levels of NUDT5 were upregulated in breast cancer cell lines and breast tumor tissues, and the expression of NUDT5 in breast tumor tissues increased significantly when compared with adjacent non-tumorous tissues by immunohistochemical staining of tissue microarrays." (PMID 33571243, 2021). "Recent studies revealed another function of NUDT5: driving nuclear ATP synthesis, which may play an important role in breast cancer." (PMID 32300600, 2020). "NUDT5 plays important roles in the estrogen signaling pathway, and thus could be involved in the pathogenesis of breast cancer." (PMID 32300600, 2020). "We have provided a proof of concept showing that TH5427 blocks NUDT5-dependent processes in breast cancer cells, and targeting NUDT5 may represent a promising new therapeutic approach for breast cancer treatment." (PMID 29343827, 2018). "NUDT5 (also called NUDIX5) has been implicated in ADP-ribose and 8-oxo-guanine metabolism and was recently identified as a rheostat of hormone-dependent gene regulation and proliferation in breast cancer cells." (PMID 29343827, 2018). "Our findings indicated that the high expression of NUDT5 is probably involved in the poor prognosis of breast cancer via the activation of the AKT / Cyclin D pathways, which could be a prognostic factor and potential target in the diagnosis and treatment of breast cancer." (PMID 33571243, 2021). "The lead compound TH5427 was shown to block progestin-dependent, PAR-derived nuclear ATP synthesis and subsequent chromatin remodeling, gene regulation and proliferation in breast cancer cells, suggesting that targeting NUDT5 may represent a novel therapeutic approach for breast cancer treatment." (PMID 32548091, 2020). "We have previously identified NUDIX5 (nucleotide diphosphate linked to moiety-X 5), more generally referred to as NUDT5 (nucleotide diphosphate hydrolase type 5), as a key regulator in hormone receptor positive and serum-starved breast cancer cells exposed to hormone." (PMID 31510016, 2019). "In silico molecular docking demonstrated strong binding affinities between major triterpenoid compounds and key breast cancer-related proteins, including HPA, MELK, CK2α, and NUDT5." (PMID 41237100, 2025).